ARRDC3 (arrestin domain containing 3)
Diseases named in the same sentence as ARRDC3 in open-access papers (continued):
Sharing a sentence is not in itself a finding about the gene and the disease.
invasive breast carcinoma (2 papers, 2018 to 2025). A carcinoma that infiltrates the breast parenchyma. "In more recent work, we found that loss of ARRDC3 expression is also responsible for defective PAR1 trafficking in invasive breast cancer, suggesting that ARRDC3 tumor suppressor function is linked to both integrin β4 and GPCR trafficking." (PMID 29954076, 2018). "In invasive breast cancer, the loss of ARRDC3 expression results in diminished PAR1 degradation and aberrant signaling, whereas ectopic expression of ARRDC3 restores PAR1 endo-lysosomal trafficking and suppresses signaling, invasion, and metastasis." (PMID 40409556, 2025). "Since ARRDC3 expression is either lost or suppressed in invasive breast cancer, we employed a lentiviral induction system to restore ARRDC3 expression in MDA-MB-231 cells." (PMID 29954076, 2018). "Similar to studies in HeLa and endothelial cells, ALIX was shown to be required for ARRDC3-mediated degradation of activated PAR1 in invasive breast carcinoma." (PMID 29954076, 2018). "In invasive breast cancer, a target of ARRDC3 is the integral membrane protein integrin β4, which is enriched in triple-negative breast cancer and a marker of poor prognosis." (PMID 29954076, 2018). "This study is the first to identify an important role of the ARRDC3 endocytic adaptor protein that functions as a tumor suppressor by regulating GPCR trafficking and signaling in invasive breast cancer." (PMID 29954076, 2018).
anhidrosis (1 paper, 2021). Lack of sweating or the ability to sweat when provoked by the appropriate stimulus. "Upregulated 6.741-fold during transient erythromycin-induced anhidrosis, the arrestin domain containing 3 (ARRDC3) gene downregulates β2-adrenergic receptors (β2-AR) by promoting retention of early endosomes and delaying recycling." (PMID 34944156, 2021).
breast tumors (1 paper, 2017). "Our results suggest that restoration of ARRDC3 expression is an important antineoplastic mechanism of SINE compounds in TNBC, and therefore selinexor could be an effective treatment option for breast tumors with down-regulated ARRDC3." (PMID 28881784, 2017).
congestive heart failure (1 paper, 2024). Failure of the heart to pump a sufficient amount of blood to meet the needs of the body tissues, resulting in tissue congestion and edema. "ARRDC3 variants have also been associated with congestive heart failure in cattle." (PMID 38097622, 2024).
endometriosis (1 paper, 2022). The growth of functional endometrial tissue in anatomic sites outside the uterine body. "In future studies, these limitations will be addressed by further expanding the number of samples and refining the experimental protocols to further understand the mechanism of the DHRS4-AS1/miR-139-5p/ARRDC3 axis in endometriosis." (PMID 35414313, 2022). "In summary, this study is the first to reveal that DHRS4-AS1 is involved in endometriosis through regulating EC-ESC proliferation, migration, invasion, and apoptosis via the miR-139-5p/ARRDC3 axis." (PMID 35414313, 2022).
epithelial ovarian cancer (1 paper, 2022). "For instance, ARRDC3, a member of the ARRDC family, served as a biomarker for the diagnosis and prognosis of epithelial ovarian cancer." (PMID 35664304, 2022). "Studies have shown that ARRDC3, an important member of the ARRDC family, was closely related to immunity in epithelial ovarian cancer, which supports our research." (PMID 35664304, 2022).
glioma (1 paper, 2025). A benign or malignant brain and spinal cord tumor that arises from glial cells (astrocytes, oligodendrocytes, ependymal cells). "Prior studies describe ARRDC3 as a tumor suppressor in other cancers, where it attenuates GPCR signaling and limits invasion, and additional evidence links ARRDC3 polymorphisms and expression to glioma susceptibility and adverse outcomes in related malignancies." (PMID 41235227, 2025).
liver disease (1 paper, 2025). "Previous work has demonstrated that the gene, Arrdc3,modulates insulin action and glucose metabolism in the liver, which may be important for metabolic disorders, including metabolic dysfunction-associated steatotic liver disease." (PMID 41007411, 2025).
lymphoma (1 paper, 2024). A malignant (clonal) proliferation of B- lymphocytes or T- lymphocytes which involves the lymph nodes, bone marrow and/or extranodal sites. "Collectively, these findings demonstrate Arrdc3 loss leads to a marked acceleration of MYC-driven lymphoma development." (PMID 38097622, 2024). "We then monitored those mice possessing an Eμ-Myc transgene to determine the impact of Arrdc3 loss on MYC-driven lymphoma development." (PMID 38097622, 2024). "This likely indicates that Arrdc3 loss may generally enhance the survival/growth of Eμ-Myc lymphoma cells, which are highly apoptosis-prone, under normal (or slightly stressful; e.g. DMSO treatment/cell sorting) conditions." (PMID 38097622, 2024). "The Eμ-MycT/+;Arrdc3−/− lymphomas were more immature in origin (>60% tumours were majority B220+/IgD-/IgM- pro-B/pre-B) compared to the Eμ-MycT/+;Arrdc+/+ lymphomas (>60% tumours were majority B220+/IgD-/IgM+ immature B)." (PMID 38097622, 2024). "Surprisingly, one Eμ-MycT/+;Arrdc3−/− animal survived post-weaning but had to be sacrificed due to lymphoma at 56 days." (PMID 38097622, 2024). "Having found that loss of Arrdc3 confers a competitive advantage in malignant Eμ-Myc lymphoma cells, and having generated an Arrdc3 knockout mouse model, we next investigated whether Arrdc3 might impact MYC-driven lymphoma development in vivo." (PMID 38097622, 2024). "Notably, the absence of ARRDC3 markedly accelerated MYC-driven lymphoma development." (PMID 38097622, 2024).
tumor (21 papers, 2012 to 2025). "Some studies have shown that protein ARRDC3 was implicated in tumor suppression by modulating the levels of carcinogenic genes." (PMID 33802957, 2021). "We selected a group of mi-RNAs (12 in total) whose roles have been implicated as tumor suppressor, and their levels are up-regulated 1.5 fold or higher by ARRDC3 expression in MDA-MB-231 cells." (PMID 31295851, 2019). "We nominate CEBPD and TNFRSF1A/ITGB1 as actionable nodes and identify ARRDC3 as a spatially restricted effector with context-dependent tumor-modulatory functions warranting therapeutic exploration." (PMID 41235227, 2025). "The tumor inhibition properties of ARRDC3 are presumably facilitated by linking target substrates such as β-adrenergic receptor and integrin β4 to E3 ligase, in which these target substrates become ubiquintinated and degraded by the proteasome." (PMID 37141193, 2023). "Our recent studies identified a group of tumor suppressing miRNAs whose expression is up-regulated 1.5-fold or higher by over-expression of ARRDC3 in TNBC cells." (PMID 32784600, 2020). "Another study using MDA-MB-231 cell (a BLBC cell line) demonstrated that SIRT2 silenced Arrestin domain-containing 3 (ARRDC3), a tumor suppressor, contributing to the aggressive nature of BLBC cells." (PMID 33014852, 2020). "We recently found that tumor suppressing activities of ARRDC3 are mainly mediated by tumor suppressing miRNAs." (PMID 32784600, 2020). "Despite the importance of ARRDC3 as a tumor and metastasis suppressor, little is known about ARRDC3 mediated transcriptional control and its target genes that contribute to its metastatic and chemo-resistance suppressing activity of ARRDC3." (PMID 31295851, 2019). "Unlike other endocytic adaptor molecules, the mechanism by which ARRDC3 functions as a tumor suppressor has been investigated." (PMID 29954076, 2018). "The ability of SINE compounds to induce cytotoxicity in TNBC cells through the induction of ARRDC3 expression suggest that in these sensitive tumor cells, the ARRDC3 mediated pathways are fully active downstream of this tumor suppressor protein." (PMID 28881784, 2017). "Consistent with in vitro findings, the restoration of ARRDC3 expression was seen in tumor specimens treated with selinexor." (PMID 28881784, 2017). "This is consistent with the ARRDC3 tumor suppressor function." (PMID 40409556, 2025). "Down-regulation of ARRDC3 promotes tumor cell proliferation and inhibits apoptosis." (PMID 38482171, 2024). "Furthermore, NaB exhibits a significant capacity to suppress the oncogene Meq and upregulates the tumor suppressive genes such as Meq and ARRDC3 in spleen, thereby positively influencing anti-tumor performance." (PMID 38482171, 2024). "Our previous studies and others have demonstrated that arrestin domain containing 3 (ARRDC3), a metastasis and tumor suppressor, is epigenetically silenced in metastatic TNBC cells, and levels of ARRDC3 in TNBC tumor tissues are significantly lower than those from benign tissues." (PMID 32784600, 2020). "ARRDC3 has been identified as a tumor suppressor in breast and prostate cancer." (PMID 29954076, 2018). "The expression of several tumor suppressive genes, such as PTEN, ARRDC3, and TGF-β, was investigated in MSB-1 cells after 24 h of NaB treatment." (PMID 38482171, 2024).
tumor (continued). "Our TMA analysis further supports this hypothesis by showing the inverse correlation between ARRDC3 and ITG β4 levels among TNBC tumor tissues." (PMID 28881784, 2017). "As multiple tumor suppressors and nuclear transcription regulators are accumulated in the nucleus as a function of SINE compounds, it will be challenging to pinpoint out the single mechanism by which ARRDC3 transcription is restored in TNBC cells." (PMID 28881784, 2017). "To identify the sub-population of TNBC patients who may potentially benefit from treatment with selinexor, we assessed the levels of ARRDC3, XPO1 and ITG β4 from normal biopsy tissue as well as in 114 biopsies of TNBC patient tumor samples." (PMID 28881784, 2017). "Based on the result that ARRDC3 expression does not affect the overall EV production, the outcome suggests that ARRDC3 is likely involved in regulation of tumor micro-environment mediated EV production (i.e., growth factors) without affecting homeostatic EV production." (PMID 30545011, 2018).
cancer (17 papers, 2017 to 2025). A tumor composed of atypical neoplastic, often pleomorphic cells that invade other tissues. "Several publications have associated abnormalities in ARRDC3 with a wide variety of cancers, particularly in epithelial to mesenchymal transition (EMT) and invasiveness, where loss/downregulation of ARRDC3 contributes to more severe phenotypes." (PMID 38097622, 2024). "ARRDC3 has been suspected to act as a potential metastasis suppressor in many human cancers and as a diagnostic and prognostic marker for ovarian cancer." (PMID 35563378, 2022). "As epigenetic changes including miRNA expression has been implicated in aggressive nature of cancers, we explored the relationship between ARRDC3 and specific miRNAs important in controlling invasive and chemo-resistant potentials of TNBC." (PMID 31295851, 2019). "It is worth mentioning that enhancing the expression of miR-200b is beneficial in sensitizing cancer cells into chemotherapy, so that arrestin domain containing 3 (ARRDC3) elevates the efficacy of chemotherapy in TNBC cells via miR-200b up-regulation." (PMID 32664703, 2020). "Among the differentially expressed genes, 5 (DUSP6, SOX9, DKK1, ARRDC3 and CSRNP2) were known to be associated with signaling pathways in cancer or cancer stem cells." (PMID 32231719, 2020). "It is possible that ARRDC3 regulates invasive potentials of cancer EVs partially through down-regulating ITG β4+ EVs and partially through ITG β4+ EV-independent mechanisms (i.e., through regulation of exosomal miRNAs or DNAs)." (PMID 30545011, 2018). "In human cancers, ARRDC3 expression is also suppressed in breast, kidney, ovarian and pheochromocytoma, while other cancers clearly show increased expression." (PMID 29954076, 2018). "We concluded that ARRDC3 expression is central for mediating the anti-cancer effects of SINE compounds." (PMID 28881784, 2017). "Our previous report that IC50 of selective inhibitors of nuclear exporter (SINEs) is inversely correlated with the levels of ARRDC3 further supports this hypothesis as restoration of ARRDC3 represents anti-cancer mechanism of SINEs." (PMID 31295851, 2019). "The androgen receptor directly regulates the transcription of miR-182-5p, which can target the 3′UTR of ARRDC3 mRNA and affect the expression of ARRDC3/ITGB4 to promote cancer." (PMID 37174715, 2023). "In this study, we investigated the anti-cancer effects of SINE compounds on TNBC models in vitro and in vivo and evaluated the role of ARRDC3 in mediating anti-cancer effects of SINE compounds." (PMID 28881784, 2017). "Moreover, augmented ARRDC3 expression inhibited GPCR-dependent activation of the Hippo signaling pathway, which is considered crucial for cancer progression." (PMID 35563378, 2022). "Based on our recent studies that ARRDC3 sensitizes TNBC cells to DNA damaging agents, we tested whether inhibition of DNA damaging responses relates to the anti-cancer mechanism of miR-489 in TNBC cells." (PMID 32784600, 2020). "Indeed, it has been recently confirmed that ARRDC3 is pivotal for metastasis suppression in triple negative breast cancer (TNBC) cells, where ITG β4 undergoes endosomal recycling and exocytosis, allowing cancer cell invasion." (PMID 35563378, 2022). "The effect of increased ARRDC3 expression in these specific cancer types is not known." (PMID 29954076, 2018).
infection (5 papers, 2020 to 2024). The state of being infected such as from the introduction of a foreign agent such as serum, vaccine, antigenic substance or organism. "We further demonstrated that H. pylori–infected AGS cells increased ARRDC3 expression in a time-dependent and infection dose–dependent manner." (PMID 32634127, 2020). "Interestingly, arrestin-related domain-containing protein-3 (ARRDC3) was significantly upregulated upon infection with SARS-CoV-2 in both cell lines." (PMID 38786015, 2024). "Infection of human primary gastric mucosa with H. pylori 26695 also increased ARRDC3 expression." (PMID 32634127, 2020). "In addition, we performed the RNA velocity analysis on an embedding of the Calu-3 cells calculated without viral genes, which is now driven by the genes induced by the infection such as IFIT2 or ARRDC3, leading to a convergence of highly infected cells independent of the virus." (PMID 33585804, 2021). "In addition, two genes, arrestin-related domain-containing protein-3 (ARRDC3) and thioredoxin-interacting protein (TXNIP), stood out among the few genes that were significantly upregulated upon infection with either viruses and in both cell lines." (PMID 33585804, 2021). "Furthermore, infection of human GEC lines with WT H. pylori or H. pylori 26695 also increased ARRDC3 expression." (PMID 32634127, 2020). "ARRDC3, a member of the arrestin family, was positively correlated with vRNA abundance, yet its depletion increased VEEV-TC-83 infection via most assays as well as VEEV-TrD infection, and its overexpression decreased infection, in contrast with the other four positively correlated genes tested." (PMID 33788849, 2021). "However, to date, the relationship between ARRDC3 and infection or inflammation has not been reported." (PMID 32634127, 2020).
inflammation (1 paper, 2020). Aberrant reaction of the microcirculation characterized by movement of fluid and leukocytes from the blood into extravascular tissues. "Importantly, gastric inflammation was attenuated in Arrdc3–/– mice but increased in protease-activated receptor 1–/– (Par1–/–) mice." (PMID 32634127, 2020).
ARRDC3 also shares sentences with these, for which no sentence is quoted: ischemic stroke (2 papers); Alzheimer disease (1); cervical cancer (1); diabetes (1); haematopoietic cancers (1); Hepatic steatosis (1); Insulin resistance (1); metabolic disorders (1); metabolic syndrome (1); omphalocele (1); preeclampsia (1); type 2 diabetes (1); vitiligo (1).